SLCO6A1 (solute carrier organic anion transporter family member 6A1)
Synonyms: CT48; GST; OATP-I; OATP6A1; OATPY; MGC26949
Tractability: Antibody: UniProt places it where antibodies can reach, with medium confidence; UniProt predicts a signal peptide or a membrane-spanning region; its Gene Ontology location is reachable by antibodies, with medium confidence.
Gene: Protein-coding gene on chromosome 5 (102,371,774 to 102,499,016, reverse strand). Ensembl gene ENSG00000205359.
Subcellular location: Cell membrane
Gene Ontology:
Molecular function: secondary active transmembrane transporter activity
Biological process: sodium-independent organic anion transport; transmembrane transport
Cellular component: basolateral plasma membrane; membrane; plasma membrane
Genetic constraint (gnomAD): Loss-of-function variants: 43 observed, 49.18 expected, observed/expected ratio (o/e) 0.87, 90% interval 0.68 to 1.13. The upper end of that interval is the gene's LOEUF score, 1.13, which puts it in group 4 of 6, group 1 being the genes least tolerant of losing a copy. Missense variants: 668 observed, 686.9 expected, observed/expected ratio (o/e) 0.97, 90% interval 0.91 to 1.04. Synonymous variants: 246 observed, 240.2 expected, observed/expected ratio (o/e) 1.02, 90% interval 0.92 to 1.14.
Homologues: Orthologues: chimpanzee SLCO6A1 (98% identical), macaque SLCO6A1 (82% identical), rabbit SLCO6A1 (58% identical), dog SLCO6A1 (56% identical), pig SLCO6A1 (54% identical), rat Slco6b1 (43% identical), rat Slco6c1 (38% identical), mouse Slco6c1 (37% identical), rat Slco6d1 (35% identical), tropical clawed frog slco4c1 (33% identical), mouse Slco6d1 (32% identical), Caenorhabditis elegans F53B1.8 (24% identical), and 2 more. Paralogues in human: SLCO4C1 (37% identical), SLCO4A1 (28% identical), SLCO5A1 (25% identical), SLCO3A1 (21% identical), SLCO1B1 (21% identical), SLCO1C1 (21% identical), SLCO1B3 (20% identical), SLCO2A1 (19% identical), SLCO1A2 (19% identical), SLCO2B1 (19% identical).
Diseases named in the same sentence as SLCO6A1 in open-access papers:
SLCO6A1 is named in the same sentence as 10 diseases in open-access papers, as found by Europe PMC text mining. Sharing a sentence is not in itself a finding about the gene and the disease. The quoted sentences say what the papers report.
breast carcinoma (1 paper, 2025). "Consistent with these advancements, our analysis reveals SETDB1, NDUFS1, ARMCX5, TRPM4, and SLCO6A1 as significantly altered genes in high-grade breast carcinomas." (PMID 41503337, 2025). "The TCGA-BRCA cohort analysis emphasizes a potential interplay of metabolic genes like NDUFS1, TRPM4, ARMCX5, SLCO6A1, and epigenetic axis genes like SETDB1 and USP37 in the oncogenesis and prognosis of breast carcinomas." (PMID 41503337, 2025). "Additionally, this study highlights two understudied genes in breast carcinoma - ARMCX5 and SLCO6A1." (PMID 41503337, 2025).
Crohn disease (1 paper, 2014). A gastrointestinal disorder characterized by chronic inflammation involving all layers of the intestinal wall, noncaseating granulomas affecting the intestinal wall and regional lymph nodes, and transmural fibrosis. "SLCO6A1 was the sole gene in the genomic region identified in that study, though the potential role for this gene in Crohn's disease is unclear." (PMID 25473852, 2014).
serous ovarian cancer (1 paper, 2018). "In serous ovarian cancer, SLCO1B1, SLCO1C1, and SLCO6A1 were observed in a low number of samples only." (PMID 30131693, 2018).
cancer (5 papers, 2013 to 2025). A tumor composed of atypical neoplastic, often pleomorphic cells that invade other tissues. "The list of 78 also included five encoding membrane proteins, namely SLCO6A1, ZP4, OR2C3, OR1N1, and OR4N2, which are potential pan-cancer targets for CAR-T and antibody-drug conjugates." (PMID 39561714, 2024). "OATP6A1, originally identified as a cancer/testis antigen also called SLCO6A1, is predominantly expressed in normal testes." (PMID 25414694, 2014). "SLCO6A1 and TRMP4 alterations in high-grade tumors highlight the potential role of cancer transportome in chemotherapeutic resistance and tumor progression." (PMID 41503337, 2025).
tumor (2 papers, 2013 to 2025). "This pattern suggests that both ARMCX5 and SLCO6A1 have a plausible role in tumor aggressiveness and therapeutic resistance." (PMID 41503337, 2025).
SLCO6A1 also shares sentences with these, for which no sentence is quoted: bladder tumors (1 paper); esophageal tumors (1); medulloblastoma (1); non-small cell lung carcinoma (1); ovarian carcinoma (1).